HIVEP2-DT (HIVEP2 divergent transcript)
Synonyms: PILA
Gene: Long non-coding RNA gene on chromosome 6 (142,946,406 to 142,957,945, forward strand). Ensembl gene ENSG00000232618.
Diseases named in the same sentence as HIVEP2-DT in open-access papers:
HIVEP2-DT is named in the same sentence as 22 diseases in open-access papers, as found by Europe PMC text mining. Sharing a sentence is not in itself a finding about the gene and the disease.
HIVEP2-DT shares sentences with these, for which no sentence is quoted: infection (24 papers); bacteremia (3); otitis media (3); Acinetobacter infection (1); chronic obstructive pulmonary disease (1); coinfection (1); corneal infection (1); cystic fibrosis (1); endocarditis (1); gastrointestinal tract infections (1); hospital-acquired infections (1); influenza (1); keratitis (1); meningioma (1); necrotizing fasciitis (1); ocular infections (1); osteoarthritis (1); otitis (1); respiratory infections (1); scoliosis (1); Sepsis (1); virus infection (1).